INS (insulin)
Diseases named in the same sentence as INS in open-access papers (continued):
Sharing a sentence is not in itself a finding about the gene and the disease.
endometrial cancer (continued). "Consistently, genetically predicted higher 30-minute postchallenge insulin levels were also associated with endometrial cancer risk (OR = 1.40, 95% CI = 1.12 to 1.76, P = .003)." (PMID 26134033, 2015). "This study provides evidence to support a causal association of higher insulin levels, independently of BMI, with endometrial cancer risk." (PMID 26134033, 2015). "Low levels of free IGF1 and high insulin levels were associated with endometrial cancer risk after adjustments for age, hormone therapy use, and estradiol levels." (PMID 24904527, 2014). "Higher fasting insulin levels have been slightly associated with higher risk of endometrial cancer (OR highest quartile vs. lowest quartile of insulin 1.64, 95%CI 1.12–2.40)." (PMID 24911052, 2014). "Significantly increased risk of colorectal, pancreatic, breast, and endometrial cancers was found in highest categories of insulin/peptide C levels." (PMID 23476808, 2013). "This would suggest that endometrial cancer risk is related to the actual blood glucose, and hence insulin, demand induced by the consumption of normal portion sizes of carbohydrates rather than the standard 50 g used to calculate GI values." (PMID 18665189, 2008). "Despite this, C-peptide, a marker of pancreatic insulin production, has repeatedly been shown to be directly related to endometrial cancer risk in well-designed studies, suggesting a key role for hyperinsulinaemia." (PMID 18665189, 2008). "Epidemiological studies have also found a positive correlation between insulin levels and risk of various cancers, such as colon, breast, and endometrial cancers." (PMID 12610512, 2003). "Adiponectin, with its insulin-sensitising and anti-inflammatory properties, plays a crucial role in reducing risk of various cancers such as breast cancer, ovarian cancer, cervical cancer, endometrial cancer, colorectal cancer, and prostate cancer." (PMID 38339282, 2024). "Whether the effects of GLP-1 agonists on bodyweight and insulin sensitivity can also translate into a reduction in endometrial cancer risk remains to be seen and should be included as a secondary outcome measure in long-term cohort studies." (PMID 38473385, 2024). "Unique pathways of F-AD switch genes were associated with viral myocarditis, Hippo signaling pathway, endometrial cancer, insulin signaling, PI3K-AKT signaling, adherens junction, gap junction, cardiomyopathy, mTOR signaling, longevity, sphingolipid signaling, apoptosis, E. coli infection." (PMID 36389068, 2022). "Furthermore, BioT and insulin mediated ~21% and ~35% correspondingly of the total association between BMI and endometrial cancer risk." (PMID 36558416, 2022). "In addition, the GSEA results showed that the genetic changes in the high-risk endometrial cancer patient group were related to the B cell receptor, insulin, JAK-STAT, MAPK and NOD-like receptor signalling pathways." (PMID 35321716, 2022). "Alcohol intake may increase endometrial cancer risk by increasing estrogen levels or may decrease endometrial cancer risk by improving insulin sensitivity and reducing fasting insulin concentrations." (PMID 34823502, 2021). "Similarly, a case–control study involving a Caucasian population in Alberta, Canada, also found that the highest quartile of insulin, in comparison with the lowest quartile, was associated with an increased risk of endometrial cancer." (PMID 29533014, 2018). "Insulin has been identified as a risk factor for endometrial cancer." (PMID 29533014, 2018). "Finally, basic science studies are needed to elucidate the mechanistic pathways that potentially explain a causal relationship between insulin levels and cancer metastasis in endometrial cancer." (PMID 29533014, 2018). "Similarly, the evidence linking endometrial cancer risk with insulin levels is helping to highlight the complex yet potentially causal relationship between risk factors for diabetes and cancer." (PMID 26540230, 2015).
endometrial cancer (continued). "These opposing mechanisms, whereby alcohol may act as an effect modifier in the hypothesized causal association between insulin exposure and endometrial cancer risk, may help to explain some contradictory findings in the literature to date." (PMID 23929278, 2013). "A low GI diet where reduction of insulin levels lowers testosterone levels, improves hirsutism and acne, improves menstrual function, dislipidaemia and potentially decreases the risk of endometrial cancer has led to support for its use in both obese and lean patients with PCOS." (PMID 21385417, 2011). "Physical activity of a moderate-to-vigorous intensity could reduce risk of endometrial cancer because it improves insulin sensitivity and reduces circulating levels of insulin." (PMID 20877336, 2010). "Sitting time may also be linked to endometrial cancer risk through these insulin-related mechanisms, as excessive sitting is associated with low levels of energy expenditure, as well as with weight gain and insulin resistance." (PMID 20877336, 2010). "Serum IGF-I, IGFBP-1, IGFBP-3 and insulin levels seem unrelated to endometrial cancer risk." (PMID 14583772, 2003). "We present here results of a population-based case–control study in Sweden, in which we assessed the relationships of endometrial cancer risk with serum levels of fasting insulin, IGF-I, and IGFBP-1, as well as IGFBP-3, IGF's major binding protein in the circulation." (PMID 14583772, 2003). "Furthermore, type II diabetes mellitus (Type II DM) – a condition associated with chronic endogenous insulin excess for many years both before and after diagnosis – is a well-established risk factor for endometrial cancer." (PMID 14583772, 2003). "Insulin inhibits IGFBP-1 synthesis in liver and other tissue, and this may be one key mechanism through which insulin increases endometrial cancer risk." (PMID 14583772, 2003). "The measurement of metabolic variability over time, such as fluctuations in body weight, insulin levels, glucose levels, leptin levels, and adiponectin levels, may provide a more accurate tool for stratifying risk of endometrial cancer than traditional static measures." (PMID 41375041, 2025). "However, whether insulin levels are related to the risk of lymph node metastasis (LNM) in endometrial cancer is unknown." (PMID 29533014, 2018). "Additionally, since obese post-menopausal women have higher circulating estrogen and insulin levels than thinner post-menopausal women, the effect of coffee in reducing endometrial cancer risk may be greatest among these women." (PMID 22254087, 2011). "PPAR-γ is involved with insulin sensitivity, adipokine and oestrogen signalling, that are pathways relevant for endometrial cancer." (PMID 40633141, 2025). "A study examining endometrial tissue from endometrial cancer patients found increased insulin levels and IGF receptor and protein expression in epithelial and stromal cells, suggesting a role in cancer cell proliferation and differentiation." (PMID 40534880, 2025). "Improved insulin sensitivity, SHBG restoration, and reestablishment of hormonal balance collectively reduce endometrial cancer risk." (PMID 41301707, 2025). "Beyond insulin sensitization, in vitro studies suggest antiproliferative and anti-metastatic effects in estrogen-dependent, endometrial carcinoma-like cells." (PMID 40114027, 2025). "Prior studies have highlighted TET1’s role in driving the proliferation of insulin-dependent endometrial cancer by enhancing G protein-coupled estrogen receptor expression and PI3K/AKT pathway activation." (PMID 39104395, 2024). "Much interest has been expressed in the re-purposing of metformin, an oral biguanide and insulin-sensitiser, in the management of endometrial cancer." (PMID 38473385, 2024). "For endometrial cancer, we estimated a positive indirect effect through estradiol (RR 1.24; 95%CI, 1.03–1.65), and a stronger indirect effect through fasting insulin (RR 1.42; 95%CI, 0.96–2.26)." (PMID 35048536, 2022).
endometrial cancer (continued). "The effect of fasting insulin on overall endometrial cancer strongly attenuated when bioavailable testosterone was included in the model (OR per increase in natural log transformed pmol/L fasting insulin 1.22, 95% CI 0.48 to 3.11, P = 6.78 × 10−1)." (PMID 35436960, 2022). "On the contrary, the following pathways were mostly enriched in the low expression group: tight junction, insulin signaling pathway, adipocytokine signaling pathway, endometrial cancer, and vasopressin-regulated water reabsorption." (PMID 35299868, 2022). "In recent years, metformin, an insulin sensitizer, has been applied by researchers in the conservative treatment of endometrial cancer." (PMID 35854762, 2022). "In mediation analyses, we found evidence that fasting insulin, bioavailable testosterone concentrations and SHBG partially mediated the effect of BMI on overall endometrial cancer risk." (PMID 35436960, 2022). "We found strong evidence for a mediating role of fasting insulin, bioavailable testosterone and SHBG in the effect of BMI on endometrial cancer risk." (PMID 35436960, 2022). "YAP inhibitors or metformin alone only partially inhibited the function of insulin and IGF1 in endometrial cancer cells, while their combination completely blocked the effects of insulin." (PMID 33178014, 2020). "Adiponectin can not only inhibit the proliferation and migration of endometrial cancer cells through the AMPK/mTOR/S6K1 signaling pathway but can also enhance the sensitivity of endometrial cancer cells to insulin through the AMPK/S6K1/IRS1 signaling pathway." (PMID 31440472, 2019). "Studies have shown that estrogen combined with insulin can significantly promote the proliferation of endometrial cancer cells compared with estrogen or insulin alone." (PMID 31440472, 2019). "Insulin levels are significantly associated with LNM risk in both premenopausal and postmenopausal women with endometrial cancer." (PMID 29533014, 2018). "In recent studies, we provided evidence that certain insulin analogs elicit differential activities in endometrial cancer cells in comparison to regular insulin or IGF1." (PMID 29615978, 2018). "The mechanisms supporting this association can be explained primarily through both the direct and indirect roles of insulin in endometrial cancer development." (PMID 29533014, 2018). "In our previous case–control study conducted in China 21, we identified insulin as an independent predictor of endometrial cancer in premenopausal women." (PMID 29533014, 2018). "In endometrial cancer patients with type 2 diabetes, metformin leads to decreased expression of the estrogen receptor in tumor tissue compared to insulin treatment." (PMID 30211120, 2018). "Insulin indirectly induces the pathogenesis of endometrial cancer by inhibiting the synthesis of sex hormone‐binding globulin (SHBG), which normally binds to androgens and estrogens." (PMID 29533014, 2018). "The other possible mechanistic links between insulin and endometrial cancer will be further elaborated upon later." (PMID 29533014, 2018). "Elevated fasting serum insulin levels and insulin responses after glucose administration have been found in postmenopausal women with endometrial cancer." (PMID 26770659, 2016). "Fourteen pathways were discovered, including the insulin signaling pathway and the endometrial cancer and estrogen signaling pathway, with enrichment p values lower than 0.05." (PMID 29083376, 2016). "Endometrial cancer is strongly related to obesity and many patients with endometrial cancer have hyperalimentation and high blood insulin." (PMID 25734181, 2015).
endometrial cancer (continued). "Using data from genome-wide association studies (GWAS) of endometrial cancer, we examine the association of single nucleotide polymorphisms (SNPs) for fasting insulin (FI), postchallenge insulin, fasting glucose (FG), BMI, and T2D with endometrial cancer." (PMID 26134033, 2015). "In the context of endometrial cancer, high concentrations of circulating insulin can exert both direct and indirect effects that contribute to the development of the tumor." (PMID 24904527, 2014). "Another case–cohort study that included 250 incident endometrial cancer patients and 465 controls assessed the association between endometrial cancer risk and serum levels of IGF1, IGFBP3, insulin, and estradiol." (PMID 24904527, 2014). "In gastric and endometrial cancer models the angiogenesis promoting effect of insulin/IGF signaling was reported to be mediated by VEGF." (PMID 24809298, 2014). "In this study, we first demonstrated that P-LAP/IRAP gene transfer increased GLUT4 expression in endometrial cancer cell lines, with resulting increases in glucose uptake into cells and the cell proliferation capacity in response to insulin." (PMID 17233921, 2007). "In summary, P-LAP/IRAP was involved in the progression of endometrial cancer mediated by insulin signaling." (PMID 17233921, 2007). "This work demonstrated that P-LAP/IRAP is involved in the increasing malignant potential of endometrial cancer mediated by insulin and to be a potential new target of molecular-targeted therapy for endometrial cancer." (PMID 17233921, 2007). "In summary, P-LAP/IRAP was involved in the increasing malignant potential of endometrial cancer mediated by insulin." (PMID 17233921, 2007). "Metformin upregulates progesterone receptors (making endometrium more sensitive to progesterone therapy), downregulates circulating insulin (insulin acts as growth factor for endometrial cancer cells), and inhibits proliferation and migration of endometrial cancer cells." (PMID 40506958, 2025). "This included colorectal (46% reduction), pancreatic (59% reduction), liver (53% reduction), gallbladder (65% reduction), kidney (24% reduction), esophageal (40% reduction), ovarian (48% reduction), and endometrial cancers (26% reduction), compared to insulin treatment." (PMID 40599584, 2025). "Additionally, insulin is a hormone with antiapoptotic activity, and endometrial cancer cell lines appear to express high-affinity insulin receptors." (PMID 40431387, 2025). "Taken together, the results of the present study indicate that the disordered proliferation of endometrial cells, which can lead to the development of endometriosis, embryonal implantation disorders, and endometrial cancer, occurs in the insulin-resistant condition." (PMID 38883605, 2024). "Additionally, metformin’s ability to improve insulin sensitivity and reduce insulin levels addresses metabolic dysregulation, a key driver of endometrial cancer." (PMID 39063589, 2024). "This could reflect mediation of the effect of fasting insulin on endometrial cancer via bioavailable testosterone, or the presence of conditionally weak instruments in this model." (PMID 35436960, 2022). "The attenuation of an effect of fasting insulin on endometrial cancer upon adjustment for bioavailable testosterone could reflect mediation of this effect or the presence of conditionally weak instrument bias in this model." (PMID 35436960, 2022). "For endometrial cancer, there was positive mediating effect through estradiol, while with less certainty, the estimates were also indicative of possible mediating effects through insulin, and leptin and CRP." (PMID 35048536, 2022). "Bariatric surgery can lower glucose levels and insulin and insulin-like growth factor-binding protein 1 (IGFBP-1); in addition, this surgery can improve insulin sensitivity in obese women and decreases inflammatory endometrial cancer risk biomarkers." (PMID 35269674, 2022).
endometrial cancer (continued). "Similarly, some of the unique pathways associated with F-AD switch genes are viral myocarditis, Hippo signaling pathway, endometrial cancer, insulin signaling, and PI3K-AKT signaling." (PMID 36389068, 2022). "Observational epidemiological studies have reported associations between several hormonal, metabolic and inflammatory factors linked to obesity and endometrial cancer, including bioavailable testosterone, sex hormone-binding globulin (SHBG), oestradiol and fasting insulin." (PMID 35436960, 2022). "It is therefore possible that glycine may be related to endometrial cancer through modification of insulin signaling." (PMID 34099314, 2021). "C-peptide, insulin, C-reactive protein, leptin, IL-1Ralpha, and IL-6 decreased significantly, while SHBG, IGFBP1, and adiponectin increased significantly in weight-loss interventions in endometrial cancer." (PMID 31440472, 2019). "Clinical studies in endometrial cancer may add further relevant information regarding the possible differential actions of insulin analogs with respect to native insulin." (PMID 29615978, 2018). "The potential contribution of exogenous insulin to endometrial cancer development remains unknown but warrants consideration." (PMID 26134033, 2015). "Specifically, insulin may promote endometrial cancer development directly as a mitogen or indirectly through its effects on estrogen availability." (PMID 22254087, 2011). "Furthermore, an in vitro study showed that endometrial cancer cells have high-affinity binding sites for insulin and proliferate in response to insulin exposure." (PMID 17233921, 2007). "The aim of this study was to examine whether the proliferation of endometrial cancer enhanced by P-LAP/IRAP is due to increased glucose uptake via the P-LAP/IRAP-mediated activation of insulin signaling." (PMID 17233921, 2007). "The aim of this study was to examine whether the malignant potential of endometrial cancer enhanced by P-LAP/IRAP is due to increased glucose uptake via the P-LAP/IRAP-mediated activation of insulin signaling." (PMID 17233921, 2007). "Their role and the role of insulin in the aetiology of endometrial cancer, is unclear." (PMID 14583772, 2003). "In addition to insulin, there is evidence that endometrial cancer development is related to alterations in insulin-like growth factor-I (IGF)-I metabolism." (PMID 14583772, 2003). "One previous case–control study showed that risk of endometrial cancer was increased among women (also nondiabetic) who had elevated fasting serum levels of C-peptide, a marker of pancreatic (pro)insulin secretion." (PMID 14583772, 2003). "Additionally, high insulin and glucose levels and stimuli promoting epithelial cell proliferation and differentiation increase the risks of endometriosis and endometrial hyperplasia leading to endometrial cancer." (PMID 38883605, 2024). "However, insulin and other anti-diabetic drugs have not been consistently associated with the risk of endometrial cancer." (PMID 34444790, 2021). "hsa_circRNA_402632 has the potential to enrich the insulin resistance pathway and hsa_circRNA_405481 affects the endometrial cancer signaling pathway, Fc epsilon RI signaling pathway, and TGF-beta signaling pathway, both of which may be related to inflammatory response." (PMID 32461970, 2020). "In view of the epidemiological and clinical correlations between the insulin/IGF1 signaling pathway and endometrial cancer risk and to explore the potential regulation of ZYG11A by IGF1, we investigated the expression of this gene in endometrial cancer-derived cell lines." (PMID 31320996, 2019). "However, they did not observe significant associations between dietary insulin scores and the endometrial cancer risk among these individuals." (PMID 31284691, 2019). "Therefore, we conducted a case–control study in China to evaluate whether insulin is a preoperative indicator of lymph node metastasis in endometrial cancer." (PMID 29533014, 2018).